TNF (tumor necrosis factor)
Diseases named in the same sentence as TNF in open-access papers (continued):
Sharing a sentence is not in itself a finding about the gene and the disease.
endometrial cancer (continued). "In order to examine how BA affects the inflammatory responses in endometrial cancer, we initially assessed the concentrations of the pro-inflammatory cytokines TNF-α and IL-1β using immunofluorescence staining." (PMID 37772231, 2023). "The aim of the study was to determine the influence of miRNAs on the expression profile of genes and proteins related to TNF-α signaling in endometrial cancer." (PMID 37233761, 2023). "The discussed miRNAs can act as a suppressor in the initial stage of endometrial cancer, which begins to gradually disappear with stimulation of the TNF-α/NF-κB axis." (PMID 37233761, 2023). "Significantly, different pathways studied such as PI3K, TGF-β signaling, TNF signaling pathway, and ACEs are present to act as objectives of inhibitors and initiate endometrial cancer growth." (PMID 37869088, 2023). "We found that the percentage of IFN‐γ+ and TNF‐α+ cells was increased in T cells when cocultured with PHF6 KD or control endometrial carcinoma cells, compared with T cells alone." (PMID 36756714, 2023). "In detail, three large case studies demonstrated a relationship between the circulating levels of TNF-α, IL-6, IL-1α, and C-reactive protein (CRP) and elevated risk of endometrial cancer." (PMID 35053431, 2022). "Immunological factors such as TNF-α, TNF receptors 1 and 2, IL-6, and C-reactive protein (CRP) have been identified as inflammatory variables associated with an increased risk of endometrial cancer in postmenopausal women." (PMID 35628566, 2022). "The addition of neutralizing TNF-α antibody reduces the estradiol mediated endometrial cancer cell invasion in both HEC 1A and KLE cell lines (p < 0.05) which indicates that TNF-α is involved in estradiol-induced endometrial cancer cell invasion." (PMID 34951691, 2022). "In endometrial cancer, both IL-6 and TNF-α have been reported to be overexpressed, and to play a role in cancer growth and metastasis, partly also by inducing ROS and subsequent DNA damage." (PMID 35053431, 2022). "In turn, IL-6 and TNF-α induce the stromal expression of hepatocyte growth factor (HGF) which in turn stimulates endometrial cancer invasion." (PMID 34951691, 2022). "No studies have examined the influence of circulating levels of IL‐6 or TNF‐α on prognostic outcomes for endometrial cancer survivors." (PMID 35174651, 2022). "In our previous work, we demonstrated that hydrogen treatment activates TNF-α and the NF-κB pathway in endometrial cancer cells." (PMID 31924176, 2020). "Preliminary data from our lab indicated that hydrogen induced TNF/NF-κB and apoptotic pathways in endometrial cancer cells." (PMID 31924176, 2020). "The level of TNF-α in circulating blood of obese patients is increased, and the increased level of TNF-α is closely related to the poor prognosis of endometrial cancer patients." (PMID 31440472, 2019). "Adipokines, such as tumor necrosis factor alpha, play an important role in initiation of endometrial cancer." (PMID 24288542, 2013). "High levels of TNFα were observed in serum and genotypic changes in the TNFα gene promoter were observed in tumor samples from endometrial cancer patients." (PMID 19784388, 2008). "Additionally, PER1 overexpression in endometrial cancer cells promotes the expression of immune factors TNF-α and IL-6, while upregulating immune checkpoints programmed death-1 (PD-1)/programmed death-ligand 1 (PD-L1)." (PMID 41451215, 2025).
endometrial cancer (continued). "The increased mRNA expression of adiponectin (ADIPOQ), leptin, IL6, and TNFα in endometrial cancer tissue highlights an enhanced inflammatory and metabolic state within the tumor microenvironment, which may drive cancer progression." (PMID 40642843, 2025). "Although the relationship between IL6 and TNFα levels and endometrial cancer appears contentious in the literature, both cytokines have been shown to promote endometrial cancer progression by facilitating cell growth, metastasis, and epithelial-mesenchymal transition (EMT)." (PMID 38339282, 2024). "TNF-α signaling in endometrial cancer is impaired, which worsens as the cancer progresses." (PMID 37233761, 2023). "On the other hand, the activation of p38-MAPK by TNFα has been mainly related to the mitogenic effects of TNFα, which could be associated with the higher risk of women with PCOS for developing an endometrial cancer." (PMID 35409282, 2022). "Estradiol stimulates TNF-α expression from the endometrial cancer cells." (PMID 34951691, 2022). "In the present study, we aimed to investigate the correlation between BMI, leptin, the proinflammatory cytokines IL-6 and TNFα, reactive oxygen species (ROS), and the traditional prognostic factors T, G, N and M status among type I endometrioid and type II endometrial cancer patients." (PMID 35053431, 2022). "The plasma levels of CA125, IL-6, and TNF-α increased in the endometrial cancer group." (PMID 35371322, 2022). "We measured CA125, IL-6, and TNF-α levels to confirm the development of endometrial cancer." (PMID 35371322, 2022). "We evaluated the information provided in articles published in English using a combination of keywords relevant to the proper adipokines, angiogenic growth factors (VEGF, FGF and IGF-1), inflammatory cytokines (TNFα, IL-6, IL-1β and IL-8) and endometrial cancer." (PMID 33799622, 2021). "Genes from blue comethylation module were enriched in pathways for Th1 and Th2 cell differentiation (adjusted p value = 6.8672 × 10−7), allograft rejection (adjusted p value = 0.0185), endometrial cancer (adjusted p value = 0.0111), and TNF signaling pathway (adjusted p value = 0.0007)." (PMID 34579086, 2021). "Additionally, local estrogen biosynthesis is promoted by TNFα induced PGC1α activity in endometrial cancer cells." (PMID 32847042, 2020). "Most of the molecular targets identified in this study are regulated by c-myc, Her2/neu, and TNF α, thus suggesting intervention of these pathways may provide a means to the development of molecular targeted therapies for endometrial cancer." (PMID 21305022, 2011). "In this study, TNF-α and Fas-L were little expressed in endometrial cancers." (PMID 12888828, 2003). "Studies of the association between the pro‐inflammatory cytokine C‐reactive protein (CRP) with endometrial cancer incidence have been mixed, and meta‐analyses of tumor necrosis factor alpha (TNF‐α) and interleukin 6 (IL‐6) have not demonstrated an association with endometrial cancer risk." (PMID 35174651, 2022). "Moreover, adipose tissue is well recognized as an active endocrine-immune organ that produces adipokines and proinflammatory mediators, mainly the inflammatory cytokines interleukin (IL)-6 and tumor necrosis factor-alpha (TNF-α), which can promote the development of endometrial cancer." (PMID 35053431, 2022). "It secretes proinflammatory cytokines, such as tumor necrosis factor-alpha (TNF-α) and interleukin-6(IL-6), that promote a chronic inflammatory condition that facilitates the development of endometrial cancer." (PMID 41383623, 2025). "Seventy-one articles reported that various cytokines, such as TGF-β, TNF-α, IL-6, etc., promoted EMT changes in ovarian, cervical, and endometrial cancers." (PMID 36766756, 2023). "For the first time, the activation of the RAS in animals with a specific overexpression of TNF demonstrates that the RAS and proinflammatory cytokines have a functionally important cross-talk in endometrial cancer." (PMID 37869088, 2023).
endometrial cancer (continued). "IL-6, Il-11, IL-31, IL-33, TNF-α, TGF-β1, SDF-1 and CXCR are involved in endometrial cancer cell growth and metastasis or involved in epithelial mesenchymal transformation (EMT) or associated with advanced disease." (PMID 34951691, 2022). "To validate this, we performed a flow cytometry experiment of PMA/ionomycin-activated and unstimulated CD8+ TIL from endometrial cancer digests including these markers plus IFN-γ, TNF-α, and IL-2 as an internal control." (PMID 32471032, 2020). "Using qRT‐PCR analysis, endometrial cancer tissues (n = 39) exhibited higher expression levels of adiponectin, leptin, IL6, TNFα, and their receptors, IL6R and TNFRSF1A/B, compared to the calibrator sample, which consisted of five pooled benign endometrial control samples." (PMID 40642843, 2025). "In addition, for TNF-α, NFKB1, and TAB2, all comparisons within endometrial cancer grades were also significant." (PMID 37233761, 2023). "However, the IFN‐γ and TNF‐α expression was similar in T cells cocultured with PHF6 KD and T cells cocultured with control endometrial carcinoma cells." (PMID 36756714, 2023). "To investigate whether PHF6 KD endometrial carcinoma cells could influence the activity of T cells, we analysed the IFN‐γ and TNF‐α expression in T cells when coculture with PHF6 KD or control endometrial carcinoma cells by flow cytometry." (PMID 36756714, 2023). "This study examined a set of six markers, namely, adiponectin, leptin, IL6, TNFα, IGF1, and IGF2 and compared them between fifty age-matched endometrial cancer patients (study group) and non-cancer patients with benign gynaecological conditions (control group)." (PMID 38339282, 2024).
measles (46 papers, 2011 to 2025). A highly contagious viral infection caused by the measles virus. "In a study, it was shown that fully vaccinated children on anti-TNFα treatment maintained seroprotection rates and antibody titers against but detected accelerated antibody loss for measles compared with the control." (PMID 41300643, 2025). "We explain to patients on TNF-alpha inhibitors that they may be at an increased risk of developing complications should they contract measles, owing to their biologic-related immunosuppression." (PMID 32258339, 2020). "In contradistinction, we explain to patients on non-TNF biologics that their risk of developing severe measles is unknown." (PMID 32258339, 2020). "KEGG pathway enrichment analysis revealed that the 557 downregulated genes were enriched in influenza A, c-type lectin receptor signaling pathway, TNF signaling pathway, measles, focal adhesion, herpes simplex infection, and FoxO signaling pathway." (PMID 37270527, 2023). "In the KEGG pathway enrichment analysis, both of these two datasets were mainly enriched in TNF signaling pathway, influenza A, NF-kappa B signaling pathway, Toll-like receptor signaling pathway, measles." (PMID 33330617, 2020). "The KEGG pathway analysis showed the up-regulated genes are significantly enriched in TNF signaling pathway, cytokine-cytokine receptor interaction, measles, influenza A, Herpes simplex infection." (PMID 33362771, 2020). "In this study, several SNPs in retinoic acid receptor α (RARB) were associated with variations in both measles antibodies and cytokine secretion levels, including IL-10, IFN-α, and TNF-α." (PMID 33167413, 2020). "Those T-cells were co-cultured for 3 days with measles primed DCs exposed to combinations of IFNβ, TNFα and IL1β." (PMID 24616721, 2014). "In the KEGG pathway enrichment analysis, both of these two datasets were mainly enriched in the TNF signaling pathway, herpes simplex infection, NF-kappa B signaling pathway, influenza A, chemokine signaling pathway, osteoclast differentiation, measles, and Toll-like receptor signaling pathway." (PMID 33330617, 2020). "In order to see if the induction of the costimulatory markers by the triple combination of IFNβ, TNFα, and IL1β has an effect on T-cell activation, we studied the induction of measles specific T-cell proliferation after co-culture with cytokine pretreated and measles primed T-cells." (PMID 24616721, 2014). "KEGG pathway annotation indicated that the most enriched pathways were measles, JAK-STAT signaling pathway, TNF signaling pathway, cytokine-cytokine receptor interaction." (PMID 30941157, 2019). "Thus, upregulated SH3BP2, TNF-α, TLR, NLR, and cytokine-cytokine receptor pathway scores and unchanged scores for measles, RLR, and IL-1β pathways in human nephrotic syndrome indicate an important role of SH3BP2-mediated innate immune activation." (PMID 38127456, 2024). "Furthermore, significant associations were shown between multiple vitamin D receptors (VDR) and retinoid X receptor α (RXRA) SNPs/haplotypes and measles-specific IL-2, IL-6, IL-10, IFN-α, IFN-γ, IFNλ-1, and TNF-α cytokine secretion." (PMID 33167413, 2020). "To determine whether the proviral effect of TNF-α is specific for HCV, we generated pseudoparticles bearing the surface glycoproteins of Lassa, measles, and vesicular stomatitis virus (VSV)." (PMID 24259385, 2014). "The administration of live vaccines (such as the oral polio vaccine; rotavirus vaccine; measles, mumps, and rubella (MMR) vaccine; and Bacillus Calmette–Guerin (BCG) vaccine) must be postponed until the age of 6–12 months in newborns exposed to anti-TNF agents during pregnancy." (PMID 35744043, 2022). "The activation scores for TLR, NLR, cytokine-cytokine receptor, and TNF-α pathways, but not RLR, IL-1β, and measles pathways, were significantly upregulated in FSGS." (PMID 38127456, 2024).
psychosis (46 papers, 2013 to 2026). "Our findings suggest that TNF-α and IL-6 are selectively associated with impairments in social cognition – specifically emotion recognition and undermentalization – in early psychosis, highlighting their potential as biomarkers and therapeutic targets." (PMID 40637145, 2025). "We investigated associations among IL-6, TNF-α, and neurocognitive performance in 107 participants: individuals at clinical high risk for psychosis (CHR-P, n = 35), first-episode psychosis (FEP, n = 39), and healthy controls (HC, n = 33)." (PMID 40637145, 2025). "Multiple linear regression models were conducted to examine the relationship among IL-6, TNF-α levels and cognitive performance while adjusting for IQ, sex, age, psychosis risk group (HC, CHR, and FEP), and positive symptom severity." (PMID 40637145, 2025). "Elevated IL-6 and TNF-α levels have also been consistently observed in individuals at clinical high risk for psychosis (CHR-P) and in first-episode psychosis (FEP) patients, suggesting their involvement in illness onset and progression." (PMID 40637145, 2025). "Other potential trait markers would be elevations of the pro-inflammatory cytokines IL-1β and TNF-α, but there is insufficient evidence of their rise in high- or ultra-high-risk states of psychosis." (PMID 36830990, 2023). "In summary, while increases in DA deficiency and TNFα cause motor PD, with the beneficial action of bilirubin, the excess DA with increased TNFα has recently been linked to Sch-related psychosis." (PMID 37511235, 2023). "A few previous studies on psychotic disorders identified an association between reduced psychomotor speed and cytokines such as interleukin (IL) -6 and tumor necrosis factor (TNF) -α." (PMID 34877553, 2021). "The elevation in TNF-α was specifically associated with increased risk for psychosis in offspring." (PMID 37123361, 2023). "TNF-α and IL-6 showed specific associations with emotion recognition and undermentalization, respectively, suggesting that proinflammatory cytokines may selectively disrupt prefrontal–limbic circuits underlying social cognition in early psychosis." (PMID 40637145, 2025). "This study aims to investigate the relationship among IL-6, TNF-α, and neurocognitive performance in early psychosis." (PMID 40637145, 2025). "Studies showed that serum levels of TNF-α and IL-1β were high in chronic patients receiving antipsychotics; nevertheless, they were low in patients with the first-episode of psychosis." (PMID 37644489, 2023). "Latest investigations reported high levels of TNF-α and IL-1β in patients with the first episode of psychosis and those taking antipsychotic agents; however, IL1-β levels decreased after remission." (PMID 37644489, 2023). "Age, sex, illness duration, smoking, and BMI were all unrelated to IL-6 and TNF-α increase in first-episode psychosis." (PMID 32256401, 2020). "Our work suggests that increases in blood cytokines, especially in IL-6, IL-8 and TNFα, persist beyond early psychosis and can be found in chronic patients even when stabilised on antipsychotic medications." (PMID 28923068, 2017). "Our findings suggest that peripheral inflammation, particularly IL-6 and TNF-α, may selectively impact social cognitive functioning in early psychosis." (PMID 40637145, 2025). "However, several studies, including meta-analyses, found elevated levels of IL-6, IL-10, and TNF-α in first-episode drug-naïve (FEDN) psychosis patients and first-episode SCZ patients, the majority of whom were using antipsychotics." (PMID 37491201, 2023). "Psychosis in amphetamine-dependent women during early cessation is associated with increases in IL-10, TNF-α, and IL-5 (the latter cytokine was not measurable in our research)." (PMID 37996407, 2023). "Serum levels of TNF-α were significantly higher in patients with agitation compared to those without, both when all patients were included in the analyses (p = 0.004) and in the psychosis group (p = 0.027)." (PMID 31509578, 2019).